BRAF (B-Raf proto-oncogene, serine/threonine kinase)
Diseases named in the same sentence as BRAF in open-access papers (continued):
Sharing a sentence is not in itself a finding about the gene and the disease.
melanoma (continued). "For example, a variant (e.g. V600E) found in a gene (e.g. BRAF) that is correlated with its biological context such as drug sensitivity (e.g. sensitive to vemurafenib) or disease phenotype (e.g. melanoma) is more meaningful than just the identified variant itself." (PMID 27074804, 2016). "Approximately 50 % of melanoma tumors have an activating mutation in BRAF V600." (PMID 27075584, 2016). "However, this changed dramatically in 2002, when the Cancer Genome Project/Sanger Institute identified oncogenic mutations in the MEK-upstream kinase BRAF in over 50% of melanoma." (PMID 27200346, 2016). "Sorafenib showed insufficient potency against melanoma even with BRAF mutation." (PMID 27152946, 2016). "In the present investigation, when sorafenib was combined with fisetin, fisetin potentiated the EMT inhibitory effect of sorafenib and effectively down regulated the expression of Twist1 transcription factor in BRAF-mutated melanoma cells in vitro as well as in xenograft tumors." (PMID 26517521, 2016). "Moreover, a combination of fisetin and sorafenib effectively reduced the Snail1 expression, resulting in a marked increase in E-cadherin expression in BRAF-mutated melanoma cells, suggesting that fisetin potentiated the EMT-inhibitory potential of sorafenib." (PMID 26517521, 2016). "Actually NRAS and BRAF mutations are the most frequent oncogenic mutations found in melanoma." (PMID 27833586, 2016). "We found that autocrine TGFβ signalling through TGFBR1 is an intrinsic requirement for the clonogenic potential of mutant BRAF transformed cells, indicating that mutation of BRAF may be useful as a biomarker for TGFβ tumour promoting activity in melanoma." (PMID 27835901, 2016). "On the basis of the evidence that these oncogenic BRAF mutations are detectable in about 50% of patients (pts) with cutaneous melanoma, research was focused on the inhibition of this pathway in order to reverse uncontrolled growth of melanoma cells." (PMID 26981153, 2016). "BRAF inhibitor (BRAFi) has been used for treatment of melanomas harboring V600E mutation." (PMID 26771234, 2016). "Interestingly, a phase I clinical trial of GDC-0941 in solid cancers showed that a melanoma patient with good response had a BRAF mutation and wild-type PIK3CA." (PMID 27465249, 2016). "Thus, this practical algorithm represents the best way in terms of adequacy, rapidity and cost-effectiveness to screen melanoma patients for BRAF V600E mutation." (PMID 27863476, 2016). "Approximately 50 % of malignant melanomas harbor activating point mutations in the BRAF gene." (PMID 27255157, 2016). "BRAF inhibitors are highly effective therapies for the treatment of BRAFV600-mutated melanoma, with the main toxicity being a variety of hyperproliferative skin conditions due to paradoxical activation of the mitogen-activated protein kinase (MAPK) pathway in BRAF wild-type cells." (PMID 27476449, 2016). "BRAF mutations were described in several other neoplasms and potent drugs have already shown a robust clinical response in melanomas, hairy cell leukemias, as well as brain tumors with BRAF p.Val600Glu such as pilocytic astrocytoma, pleomorphic xanthoastrocytoma and ganglioglioma." (PMID 26927026, 2016). "Thus vemurafenib and trametinib respectively are used to target melanoma cells with BRAF and MEK gene mutations." (PMID 27270229, 2016). "Thus, therapies were developed to specifically target (“targeted therapies”) melanomas harboring either the BRAF or the NRAS mutation." (PMID 27833586, 2016). "Therefore, the effect of dssPLA2 on melanoma should be evaluated in several aspects, especially resistance mechanisms focusing on BRAF V600E mutation gene and BRAF protein." (PMID 26884744, 2016). "Therefore, our study suggests that RASA1 inactivation and subsequent R-Ras activation is one of the possible mechanisms leading to Ral-A activation in melanomas with BRAF mutation." (PMID 26993606, 2016).
melanoma (continued). "Samples were analyzed using the Sequenom MassARRAY MelaCarta panel of recurrently mutated melanoma genes, and also by direct Sanger sequencing of BRAF exon 15, which served to identify the full extent of BRAF exon 15 mutations, and to provide validation of the BRAF MelaCarta mutation data." (PMID 27191502, 2016). "A phase II trial investigated the effect of vemurafenib in BRAF-mutated non-melanoma tumors." (PMID 28050231, 2016). "Vemurafenib is a BRAF-specific inhibitor used in the therapy of BRAF mutated melanoma patients." (PMID 27388771, 2016). "However, activity of BRAF inhibitors in this context has been reported in BRAFV600R-mutated melanoma cell lines and in a small Australian patient series." (PMID 27255157, 2016). "Therefore, NRAS exon 2 and BRAF exon 15 variants represented the two most frequently mutated exons in NZ melanomas." (PMID 27191502, 2016). "Mutations in the BRAF signaling pathway have been identified as one of the drivers of melanoma." (PMID 27075584, 2016). "As an example, the use of tyrosine kinase inhibitors for chronic myeloid leukemia can lead to mutations in the BCR-ABL protein (T315I), which confer resistance to the drug; in melanoma, the efficacy of BRAF inhibitor can be abolished by mutations in BRAF or other alternative pathways." (PMID 27761200, 2016). "Likewise, the MART-1+ xMD procured melanoma cells demonstrated an approximate 2-fold BRAF mutation enrichment via pyrosequencing (14–33% vs. 8–9%)." (PMID 26999048, 2016). "Combinations of BRAF plus MEK inhibitors (e.g., dabrafenib plus trametinib, as well as vemurafenib plus cobimetinib) have shown an overall response rate of 66–70 % in patients with BRAF-mutated advanced melanoma and are now approved for this indication by the US FDA." (PMID 27532019, 2016). "BRAF mutations are usually detected in approximately 40-50% of melanomas." (PMID 27191502, 2016). "In contrast, BRAF mutations are rarely found in uveal melanomas or melanomas arising from the mucosa or internal organs, and mutations in the receptor tyrosine kinase KIT are found more frequently in lentigo maligna melanoma, acral melanoma and melanomas arising from the mucosa or internal organs." (PMID 27057633, 2016). "In addition to the traditional treatments based on chemotherapy, molecularly targeted drugs such as BRAF or MEK inhibitors have recently been developed and have shown clinical benefit in BRAF-mutated melanomas." (PMID 26909610, 2016). "Moreover, we observed a secondary T790M EGFR mutation in lung adenocarcinoma (LUAD) and resistance to EGFR-targeted therapies (Gefitinib and Afatinib), as well as resistance of NRAS mutated melanoma patients to a BRAF inhibitor." (PMID 27397505, 2016). "In addition, the involvement of RUNX2 in the regulation of four different RTKs implicated in melanoma progression and acquired resistance to BRAF V600E inhibitors suggests that RUNX2 is a potential therapeutic target in patients with melanoma." (PMID 27102439, 2016). "A375 is a commonly used model of melanoma associated with mutant BRAF." (PMID 26871475, 2016). "Furthermore, melanomas harbouring NRAS or BRAF mutations were associated with a trend towards worse survival and a greater likelihood of brain metastases at the time of initial diagnosis." (PMID 27213536, 2016). "We collected CSF from patients with BRAF V600E or K-mutated melanoma (N=8) or BRAF V600E mutated Erdheim-Chester Disease (ECD) (N=3) with suspected central nervous system (CNS) involvement on the basis of neurological symptoms (10/11), MRI imaging (8/11), or both." (PMID 27863426, 2016). "We collected the clinical data and mutational status of 1170 patients with advanced melanoma and established three different predictive models (binary logistic regression, classification and regression trees, and random forest) to forecast the BRAF status." (PMID 27150060, 2016).
melanoma (continued). "Approximately 40%–50% of melanoma patients have activating mutations in BRAF at valine 600 (90% are BRAFV600E) and another 15%–25% have mutations in the neuroblastoma RAS viral oncogene homolog (NRAS), and either alteration results in constitutive activation of the MAPK pathway." (PMID 27598148, 2016). "BRAF is a proto-oncogene that is mutated in approximately 50% of patients with melanoma." (PMID 27200295, 2016). "Comparison of fragment lengths from cell-free DNA between a melanoma patient and healthy controls found that the BRAF V600E mutant allele occurred more commonly at a shorter fragment length than the fragment length of the wild-type allele (132–145 bp vs. 165 bp, respectively)." (PMID 27428049, 2016). "Several targeted therapies are now available for BRAF-mutated melanoma." (PMID 27152946, 2016). "BRAF mutation testing was performed in only 57 of the total 170 melanoma patients." (PMID 27714434, 2016). "The V600E mutation is the most common form of the BRAF mutation in human melanoma." (PMID 29061943, 2015). "Finally, we demonstrated that Nodal expression is maintained and targetable in BRAF(V600E) mutation-positive melanoma cells surviving anti-BRAF treatment with vemurafenib." (PMID 26460952, 2015). "Taking A375 advanced melanoma cells as an example, we detected and validated mutations in BRAF, FGFR2 and mTOR that could reasonably be expected to associate with Vemurafenib (BRAFi (V), hereafter), Vargatef (FGFR2i (Va)) and Everolimus (mTORi (E))." (PMID 26327537, 2015). "With loss of NF1 and more recently an increase of CDK2 (in association with MITF) in melanomas being involved in the resistance to BRAF-inhibitor (BRAFi) therapy, we next sought to investigate whether miR-514a might be involved in this process." (PMID 25980496, 2015). "BRAF mutation analysis is now mandatory to identify patients affected by non resectable or metastastic melanoma who may benefit from Tyrosine Kinase Inhibitors." (PMID 26690267, 2015). "MiR-21-mediated inhibition of Sprouty may thus promote mutated BRAF/NRAS signaling of melanoma cells." (PMID 26116372, 2015). "In this study, we categorized BRAF mutations detected in NSCLCs, CRCs and melanomas into kinase-activated mutants (75 %), kinase-impaired mutants (15 %) and kinase-unknown mutants (10 %) according to the functional studies reported in the literature." (PMID 26498038, 2015). "TERT promoter mutations are known to be more common in BRAF or NRAS mutated tumors compared to WT melanomas and trend towards worse OS, however the role of TERT mutations in MBM is also unknown." (PMID 26597176, 2015). "It was reported that BRAFV600 mutated melanoma had aberrant DNA methylation activity and that BRAF inhibition could reverse the DNA methylation of some genes." (PMID 26304929, 2015). "While some authors show that the induction of autophagy and apoptosis is independent of the BRAF or NRAS mutation status of cells, others report that metformin increases tumor growth of BRAF mutated melanoma xenografts by up-regulation of VEGF-A and induction of angiogenesis." (PMID 25504439, 2015). "The frequent chromosome 7 aneuploidy may be the cause or the consequence of BRAF mutations in melanomas." (PMID 26141748, 2015). "Furthermore, we provide evidence that inhibition of mutated BRAF using the specific small molecule inhibitor vemurafenib increased the OXPHOS dependency of BRAF mutant melanoma cells." (PMID 26500770, 2015). "Moreover, we characterize several novel variants of known oncogenes like BRAF and relate molecular features of new potential drivers of melanoma to recurring features observed in other cancer tissues." (PMID 25600636, 2015). "However, mutations in BRAF alone rarely trigger melanoma and additional genetic events in BRAF-mutant cells, such as activation of AKT3, elicit a fully cancerous phenotype." (PMID 25595898, 2015).
melanoma (continued). "Initially reported as a point mutation (V600E) in the majority of metastatic melanomas, other alterations in the BRAF gene have now been reported in a variety of human cancers including papillary thyroid cancer, colon carcinomas, hairy cell leukemia, and more recently in gliomas." (PMID 25785246, 2015). "Although drugs selectively inhibiting BRAFV600E signaling could achieve dramatic clinical responses in melanoma patients with the BRAF mutation, most patients appear to eventually relapse." (PMID 26033450, 2015). "Importantly, a cell line developed from BRAF V600E-mutated PDA was equally sensitive as melanoma cells to FDA-approved BRAF inhibitor PLX-4032." (PMID 25855536, 2015). "Finally, a patient with melanoma had a BRAF V600E mutation in the tissue, but a BRAF V600K mutation in cfDNA; however, repeated testing of tumor tissue with BEAMing confirmed a BRAF V600K mutation." (PMID 25980577, 2015). "Interestingly, in two melanomas (Ht9b and Ht13) we detected the BRAF V600E mutation, which is a predictor for clinical efficacy of RAF inhibitors such as vemurafenib today." (PMID 26252375, 2015). "Our results suggest that KDR may be a predictive marker of vemurafenib and or MEK inhibitor response and the combination of cediranib and BRAF or MEK inhibitors are an actionable combinatorial regimen for melanoma patients with BRAF mutations." (PMID 26461489, 2015). "Furthermore, YAP suppression enhanced MEK inhibition in murine xenografts of human NSCLC, melanoma, and pancreatic adenocarcinoma with BRAF or KRAS mutations." (PMID 26389076, 2015). "We show here that only two thirds of BRAF V600E melanomas have a heterozygous mutation." (PMID 26141748, 2015). "In a subsequent phase III study (COMBI-d), 423 previously untreated and unresectable stage IIIC or stage IV melanoma patients with BRAF V600E or V600K mutation were randomized to receive combination of dabrafenib (150 mg BID) and trametinib (2 mg QD) or dabrafenib and placebo." (PMID 27508107, 2015). "The second question we have addressed is whether a combinatorial approach with two different antibodies directed against distinct ErbB3 surface epitopes can better inhibit receptor function in BRAF mutated melanomas." (PMID 26208478, 2015). "Activity was also noted in melanomas with activating BRAF or NRAS mutations." (PMID 26726315, 2015). "Finally, the selective targeting of BRAF activating mutations, which occur in about half of melanomas, with vemurafenib, dabrafenib, and trametinib, is associated with marked clinical activity and improved OS compared with chemotherapy." (PMID 26052356, 2015). "The disparity in the prevalence of BRAF mutation may result from differences in the role of UV exposure in the pathogenesis of human and canine melanoma." (PMID 29061943, 2015). "BRAF mutation (mt) was also evaluated in individual melanoma specimens and as well as the TMA." (PMID 26085332, 2015). "In order to provide the most clinically relevant assessment of the combination of an Aurora A kinase and MEK inhibitor in human tumor xenograft experiments, the MEK inhibitor trametinib, which is approved for clinical use in BRAF-mutated, advanced melanoma, was substituted for TAK-733." (PMID 26136684, 2015). "A series of subsequent breakthroughs in targeted therapy also led to the approval of agents targeting BRAF (vemurafenib and dabrafenib) in patients harboring active BRAF V600 mutations in melanoma and of those targeting MEK (trametinib), as well as the programmed death 1 pathway (PD-1)." (PMID 26460952, 2015). "Conversely, treatment of the BRAF-mutated G-361 melanoma tumors produced highlyremarkable data." (PMID 25595904, 2015). "A subset of patients with advanced melanoma may harbor only a BRAF mutation and achieve a durable CR on BRAF pathway inhibitors." (PMID 25886620, 2015).
melanoma (continued). "Finally, as BRAF somatic mutations characterize other human malignancies including colon cancer and melanoma, future research should clarify if the BRAF-mediated AHR activation is peculiar of PTC or a more general mechanism." (PMID 26392334, 2015). "To assess whether a new clone with BRAF V600E mutation loss could have developed we performed a tumor biopsy, that confirmed the diagnosis of melanoma metastases and, interestingly, the maintenance of BRAF V600E mutation in the new soft tissue nodules." (PMID 25810704, 2015). "Traditionally, molecular testing for a relatively small panel of genes was conducted in a histologically-defined subset of patients to determine therapy (e.g. BRAF mutation testing in patients with melanoma, HER2 immunohistochemical staining in patients with breast cancer)." (PMID 26418953, 2015). "To date, the frequency of rare BRAF activating mutations reported in melanoma ranges from 5–12%." (PMID 26690267, 2015). "We used A375 and SK-MEL-28 melanoma cells, both of which harbor BRAF mutation at V600E." (PMID 26497853, 2015). "Pembrolizumab (MK-3475, formerly called Lambrolizumab) was FDA approved in September 2014 for use in relapsed or refractory malignant melanoma following treatment with Ipilimumab or after treatment with Ipilimumab and a BRAF inhibitor in patients who carry a BRAF mutation." (PMID 26060497, 2015). "Indeed, we found that the locus coding for RICTOR is frequently amplified in melanoma independently of BRAF or NRAS mutations and that RICTOR amplification in BRAF mutated melanoma is associated with PTEN LOH." (PMID 26356562, 2015). "Lastly, we note that our study has a much larger percentage of BRAFV600E/V600E melanomas compared to other studies, which could explain why BRAF zygosity had a stronger association with sensitivity to PLX4720 treatment in our study compared to others." (PMID 26405815, 2015). "For the FDA-approved targeted therapies, there is a wide range of response rates, from approximately 30% with trastuzumab in breast cancer with HER2/Neu overexpression and/or gene amplification, 60% with vemurafenib in melanoma with a BRAF mutation, to over 90% in chronic myeloid leukemia." (PMID 26270481, 2015). "Indeed, the importance of targeting this pathway for melanoma treatment using specific BRAF inhibitors has been successfully demonstrated in BRAF V600-mutated melanoma in preclinical models and, more importantly, in clinical trials." (PMID 25789737, 2015). "NGS identified potentially actionable DNA alterations that could account for resistance in patients with BRAF mutation-positive advanced melanoma who achieved a PR or CR but whose tumors later progressed." (PMID 25886620, 2015). "The oncogenic BRAF(V600E) mutation is common in melanomas as well as moles." (PMID 26091525, 2015). "BRAF inhibitors target specific mutations of BRAF in the kinase domain, which are present in about 50% of melanomas and cause over-activation of the mitogen-activated protein kinase (MAPK)/extracellular-signal-regulated kinase (ERK) pathway, involved in cell proliferation/survival." (PMID 26090340, 2015). "The Sk-Mel-28 cell line is BRAF mutated, BRAF is mutated in 41% of melanomas (range 22–72%)." (PMID 26201960, 2015). "Over 50% of melanomas are characterized by the presence of a BRAF mutation." (PMID 25886620, 2015). "BRAF mutations are frequently observed in melanoma and in colorectal cancer." (PMID 26431495, 2015). "Finally, LGX818 a highly potent BRAF inhibitor has been studied and developed for BRAF-mutated advanced melanoma." (PMID 26431495, 2015). "In addition, the mRNA expression of these ETS genes was correlated with ERK activity in melanoma and colon cancer cell lines with activating mutations in BRAF (V600E), such that their expression decreased upon MEK inhibitor treatment." (PMID 26683696, 2015).